TNFRSF1B (TNF receptor superfamily member 1B)
Description:
Receptor with high affinity for TNFSF2/TNF and approximately 5-fold lower affinity for homotrimeric TNFSF1/lymphotoxin-alpha. The TRAF1/TRAF2 complex recruits the apoptotic suppressors BIRC2 and BIRC3 to TNFRSF1B/TNFR2. This receptor mediates most of the metabolic effects of TNF. Isoform 2 blocks TNF-induced apoptosis, which suggests that it regulates TNF function by antagonizing its biological activity.
Synonyms: CD120b; TNFBR; TNFR2; TNFR80; TNF-R75; TNF-R-II; p75; TBPII; TNFR1B; p75TNFR
Tractability: Antibody: its Gene Ontology location is reachable by antibodies, with high confidence; UniProt places it where antibodies can reach, with medium confidence; UniProt predicts a signal peptide or a membrane-spanning region.
Target class: Membrane receptor
Gene: Protein-coding gene on chromosome 1 (12,166,977 to 12,209,228, forward strand). Ensembl gene ENSG00000028137.
Subcellular location: Cell membrane (Isoform 1); Secreted (Isoform 2); Secreted (Tumor necrosis factor-binding protein 2)
Pathways (Reactome):
Immune System: Interleukin-10 signaling; Interleukin-4 and Interleukin-13 signaling; Neutrophil degranulation; TNFR2 non-canonical NF-kB pathway; TNFs bind their physiological receptors
Gene Ontology:
Molecular function: protein binding; tumor necrosis factor binding; ubiquitin protein ligase binding; tumor necrosis factor receptor activity
Biological process: cellular response to lipopolysaccharide; positive regulation of membrane protein ectodomain proteolysis; activation of NF-kappaB-inducing kinase activity; aortic valve development; extrinsic apoptotic signaling pathway; glial cell-neuron signaling; intrinsic apoptotic signaling pathway in response to DNA damage; negative regulation of extracellular matrix constituent secretion; negative regulation of neuroinflammatory response; positive regulation of apoptotic process involved in morphogenesis; positive regulation of myelination; positive regulation of oligodendrocyte differentiation; pulmonary valve development; regulation of cytokine production involved in immune response; regulation of myelination; regulation of neuroinflammatory response; regulation of T cell cytokine production; regulation of T cell proliferation; tumor necrosis factor-mediated signaling pathway; inflammatory response; negative regulation of cardiac muscle hypertrophy
Cellular component: membrane raft; plasma membrane; membrane; specific granule membrane; tumor necrosis factor receptor superfamily complex; extracellular region
Genetic constraint (gnomAD): Loss-of-function variants: 19 observed, 43.74 expected, observed/expected ratio (o/e) 0.43, 90% interval 0.3 to 0.64. The upper end of that interval is the gene's LOEUF score, 0.64, which puts it in group 2 of 6, group 1 being the genes least tolerant of losing a copy. Missense variants: 541 observed, 611.39 expected, observed/expected ratio (o/e) 0.88, 90% interval 0.82 to 0.95. Synonymous variants: 252 observed, 257.65 expected, observed/expected ratio (o/e) 0.98, 90% interval 0.88 to 1.09.
Homologues: Orthologues: chimpanzee TNFRSF1B (99% identical), pig TNFRSF1B (74% identical), macaque TNFRSF1B (73% identical), dog TNFRSF1B (71% identical), rabbit TNFRSF1B (64% identical), mouse Tnfrsf1b (62% identical), guinea pig TNFRSF1B (62% identical), rat Tnfrsf1b (62% identical), zebrafish tnfrsf11a (15% identical), zebrafish tnfrsf1b (15% identical), zebrafish cd40 (13% identical). Paralogues in human: TNFRSF8 (22% identical), TNFRSF21 (20% identical), LTBR (19% identical), TNFRSF11A (18% identical), TNFRSF4 (16% identical), CD40 (16% identical), TNFRSF1A (16% identical), TNFRSF11B (15% identical), NGFR (15% identical), TNFRSF6B (14% identical), TNFRSF14 (13% identical), TNFRSF25 (12% identical), and 9 more.
Diseases named in the same sentence as TNFRSF1B in open-access papers:
TNFRSF1B is named in the same sentence as 340 diseases in open-access papers, as found by Europe PMC text mining. Sharing a sentence is not in itself a finding about the gene and the disease. The quoted sentences say what the papers report.
autoimmune disease (67 papers, 2011 to 2025). A disorder resulting from loss of function or tissue destruction of an organ or multiple organs, arising from humoral or cellular immune responses of the individual to their own tissue constituents. "Several studies have proposed that genetic variation in TNFRSF1A and TNFRSF1B was associated with susceptibility to inflammatory and autoimmune diseases, such as tuberculosis, systemic lupus erythematosus, rheumatoid arthritis and Crohn's disease." (PMID 23029405, 2012). "Recent studies proposed that genetic variation in TNFRSF1A and TNFRSF1B was associated with susceptibility to inflammatory and autoimmune diseases, such as tuberculosis, systemic lupus erythematosus, rheumatoid arthritis and Crohn's disease." (PMID 23029405, 2012). "Indeed, TNFRSF1B deficiency could, in some cases, worsen autoimmune diseases, and TNFRSF1B agonists might have opposite effects." (PMID 38291238, 2024). "TNFRSF1B, a TNF receptor, is associated with T-cell responses, and it participates in protective immunity, inflammatory disease, and autoimmune diseases." (PMID 36588791, 2022). "Since 1998, Enbrel (TNFRSF1b-Fc fusion protein) has been a marketed product for the treatment of autoimmune disease." (PMID 30563566, 2018). "For treating autoimmune diseases, TNFRSF1B is a powerful therapeutic target." (PMID 35965557, 2022). "Accumulating evidence indicates that TNF receptor (TNFR) family member, TNFRSF1B (TNFR2), which is sustained T cell responses, plays important role in protective immunity, inflammatory, and autoimmune diseases." (PMID 33833618, 2021).
rheumatoid arthritis (51 papers, 2005 to 2025). A chronic, systemic autoimmune disorder characterized by inflammation in the synovial membranes and articular surfaces. "As for TNFRSF1B, the SNP M196R/T587G has proved predictive of Crohn's disease, systemic lupus erythematosus and rheumatoid arthritis." (PMID 20646319, 2010). "Specific polymorphisms in the human TNFRSF1B gene of which one was shown to impair TNFR2 signaling are associated with inflammatory bowel disease, ankylosing spondylitis, lupus and/or rheumatoid arthritis, supporting the idea that TNFR2 protects against these diseases." (PMID 35844585, 2022). "TNFRSF1B is a TNF-α receptor related to inflammatory diseases, such as rheumatoid arthritis." (PMID 34926700, 2021).
colitis (42 papers, 2012 to 2026). Inflammation of the colon. "Several of those pairs involve TNFRSF1B, encoding for the tumor necrosis factor receptor 2, and a genetic risk factor for colitis." (PMID 38225383, 2024). "Similarly, a seven-day DHA treatment reduced the gene expression levels of IL-1 β and TNF receptor superfamily member 1b (Tnfrsf1b) in mice with DSS-induced colitis." (PMID 38672464, 2024). "According to some researches, TNFRSF1B may contribute to colitis by promoting inflammation." (PMID 37169818, 2023).
ovarian carcinoma (41 papers, 2009 to 2025). A malignant neoplasm originating from the surface ovarian epithelium. "Blockade of TNFRSF1B has been shown to reduce tumor growth by remodeling the immune microenvironment in mouse models of ovarian cancer." (PMID 40236693, 2025). "At present, abnormal expression of Tnfrsf1b has been identified in at least 25 tumors, such as colon cancer, ovarian cancer, cutaneous T-cell lymphoma (CTCL), etc." (PMID 36118769, 2022). "The results very well corroborate with the recent reports on ovarian cancer (OC) and androgenetic alopecia (AGA) that Tnfrsf1b is a novel therapeutic target." (PMID 40869347, 2025). "In ovarian cancer patients, the presence of an exhausted subpopulation of CD8+ TNFRSF1B+ T-cells is a marker of poor prognosis." (PMID 40236693, 2025). "Clinicopathological features in ovarian cancer (OC) patients and the correlation with CD3+CD8+TNFRSF1B+ subpopulation ratio." (PMID 37712139, 2023).
breast carcinoma (40 papers, 2008 to 2026). "The TNF receptor, TNFRSF1B, has been associated with the progression of esophageal carcinoma, non-small cell lung cancer, and breast cancer." (PMID 34688260, 2021). "In TNFRSF1B, the rs1061622 GT genotype and the G allele conferred a reduced susceptibility to breast cancer (P = 0.000662, OR = 0.706, 95% CI: 0.578–0.863; P = 0.002, OR = 0.769, 95% CI; 0.654–0.905, respectively)." (PMID 25010932, 2014). "In the current case-control study, we determined the associations between potentially functional SNPs in the TNF-α, TNFRSF1A and TNFRSF1B genes and breast cancer susceptibility." (PMID 25010932, 2014). "Our results suggest that rs1061622 and rs1061624 in TNFRSF1B may affect breast cancer risk, and SNPs in TNFRSF1A are associated with the clinical features of breast cancer." (PMID 25010932, 2014). "However, to our knowledge, there are no published studies regarding the relationship between potentially functional SNPs in the TNFRSF1A and TNFRSF1B genes and the susceptibility to breast cancer among Asian populations." (PMID 25010932, 2014). "To better understand the roles of single nucleotide polymorphisms (SNPs) in the TNF-α, TNFRSF1A and TNFRSF1B genes in the development of breast cancer, we explored the associations between SNPs in these three genes and breast cancer susceptibility in northeast Chinese Han women." (PMID 25010932, 2014). "Taken together, the current study showed that the rs1061622 and rs1061624 in TNFRSF1B as well as some haplotypes might affect breast cancer susceptibility." (PMID 25010932, 2014). "In colorectal cancer tissue, the expression of TNFR2 was correlated with Ki-67 expression and a resistance to adriamycin in breast cancer, but the functional consequences of TNFR2 expression and of TNFRSF1B c.587T>G SNV on CM cells remain to be elucidated." (PMID 38474115, 2024). "We then detected the expression of TNFRSF1B on exhausted T cells in published single‐cell RNA sequencing data from breast cancer, intrahepatic cholangiocarcinoma, and other OC studies." (PMID 37712139, 2023). "TNFRSF1B expressed higher in infiltrating breast tumors, which suggest that increased TNFRSF1B expression would be a factor for a poor prognosis in breast cancer patients." (PMID 25010932, 2014). "Moreover, in breast cancer cell lines, blocking TNFRSF1A or TNFRSF1B with specific antibodies impairs tumor survival signaling and the biological function of TNF-α." (PMID 25010932, 2014). "Consistent with this hypothesis, MDA-MB-231 and MCF7 breast cancer cells with high levels of GalCer showed lower activity of the TNFRSF1B and TNFRSF9 promoters than cells lacking GalCer." (PMID 38254878, 2024).
diabetes (34 papers, 2007 to 2026). "Given its involvement in both cancer and metabolic disease, TNFRSF1B holds potential as a biomarker for identifying at-risk BC patients with diabetes and guiding personalized treatment strategies." (PMID 40547917, 2025). "It contributes to shared inflammatory pathways by promoting a pro-inflammatory microenvironment, and the presence of missense mutations in TNFRSF1B among BC patients with diabetes may exacerbate both tumor progression and metabolic dysfunction." (PMID 40547917, 2025). "They identified a panel of six genes, including FOXP3, TNFRSF1B (CD120b) and LRRC32 (GARP), which were directly linked to Treg function and stability and were differentially expressed in Tregs from individuals with diabetes." (PMID 28770318, 2017). "As chronic inflammation is a common feature of both BC and diabetes, TNFRSF1B may represent a molecular link between these diseases." (PMID 40547917, 2025).
lung carcinoma (29 papers, 2011 to 2025). "The TNFRSF1B c.587GG genotype was associated with a better OS of patients with lung cancer." (PMID 38474115, 2024). "Downregulation of TNFRSF1B (a member of the tumor necrosis factor gene family) in association with colorectal cancer here is consistent with prior studies showing lower mRNA expression of TNFRSF1B in lung cancer compared with normal lung tissue." (PMID 39227979, 2024). "We found four proteins associated with cancer that in observational long time-to-diagnosis analyses, and cis-pQTL and exGS analyses; CD74 and TNFRSF1B were associated with NHL, and ADAM8 and SFTPA2, were associated with risk of leukaemia and lung cancer, respectively." (PMID 38750076, 2024). "Hypermethylation of genes such as COX7A1, TNFRSF1B, and BDNF, as well as hypomethylation of genes such as CDC6 and KRT8, may be associated with lung cancer compared to benign nodules." (PMID 39036344, 2024). "The roles of these TNFRSF1B SNVs in the outcomes of patients with lung cancer, non-Hodgkin lymphoma, and esophageal carcinoma remain controversial, and their impacts on the outcomes of patients with CM are unknown." (PMID 38474115, 2024). "Another possibility is that this SNP may change the expression level of TNFRSF1B and influence the character of immunological response to infection in lung cancer patients, finally resulting in the difference of survival in NSCLC." (PMID 21995493, 2011). "Up to now, no published study investigated the association between TNFRSF1B +676 T>G (rs1061622) and lung cancer survival, and the exact biological mechanism underlying this association in our study remains to be investigated." (PMID 21995493, 2011).
psoriasis (22 papers, 2011 to 2025). An autoimmune condition characterized by red, well-delineated plaques with silvery scales that are usually on the extensor surfaces and scalp. "Similar to RA and IBD patients, studies have identified genetic variants linked to variable response to TNFi in psoriasis patients; one example is the TNFRSF1B c.196T>G (rs1061622) SNP, which was associated with a higher risk of poor response to TNFi in psoriasis patients of European ancestry." (PMID 40469293, 2025). "Similarly, the rs1061624 SNP in the TNFRSF1B gene, featuring the T allele, was linked to psoriasis susceptibility, potentially disrupting the TNF receptor signaling and promoting chronic inflammation." (PMID 37569685, 2023). "A previous study conducted on Psoriasis patients from the European population reported that variants in the TNF -857C and TNFRSF1B 676T genes were associated with positive response when treated with Etanercept." (PMID 40469293, 2025). "The genes associated with psoriasis that encode regulators of the NF-kB pathway include TNFAIP3, TNFRSF1B, TNIP1, TRAF1IP2, and NF-κ-BIA." (PMID 37569685, 2023). "The psoriasis lesion samples showed decreased expression of BTK and TNFRSF1B compared to controls." (PMID 33324666, 2020).
type 2 diabetes (22 papers, 2011 to 2026). "In view of this, we performed a comprehensive association analysis of TNFRSF1B variants with type 2 diabetes in 4,200 Indo-European subjects from North India." (PMID 21849023, 2011). "Only a solitary report suggested association of (CA)n repeat polymorphism of TNFRSF1B with diabetic neuropathy, while another study refuted its role in type 2 diabetes." (PMID 21849023, 2011). "We then investigated the effect of TNFRSF1B polymorphisms on quantitative metabolic traits related to type 2 diabetes viz BMI, WHR, HbA1c, fasting glucose, insulin, C-peptide, total cholesterol, TG, HDL-C, LDL-C, urea, uric acid and creatinine." (PMID 21849023, 2011). "Here, we carried out a comprehensive association analysis of TNFRSF1B variants with type 2 diabetes in Indo-Europeans." (PMID 21849023, 2011). "In view of this, we performed association analysis of seven SNPs of TNFRSF1B with type 2 diabetes in Indo-Europeans, followed by a replication analysis of three SNPs in an independent study population of Indo-European subjects from North India." (PMID 21849023, 2011). "This suggests TNFRSF1B as an important biological candidate gene for type 2 diabetes in Indo-Europeans." (PMID 21849023, 2011). "Genetic variation in or near Tnfrsf1b might predispose clinical neuropathy, reduced glycosylated hemoglobin, and increased HDL cholesterol in type 2 diabetes patients." (PMID 26529237, 2015). "The inconsistent reports suggest that the role of TNFRSF1B variants in the pathogenesis of type 2 diabetes is not clear yet, necessitating comprehensive evaluation of TNFRSF1B variants." (PMID 21849023, 2011). "The present two-stage association analysis did not detect any association between type 2 diabetes and TNFRSF1B genetic variants in Indo-Europeans from North India." (PMID 21849023, 2011). "Our two-stage association analysis suggests that TNFRSF1B variants are not the determinants of genetic risk of type 2 diabetes in North Indians." (PMID 21849023, 2011). "Among URGTG, three genes, AKT1S1, TNFRSF1B, and CACNA1A, were found to be associated with obesity-related pathways (in KEGG database), which were thermogenesis (hsa04714), the adipocytokine signaling pathway (hsa04920), and type II diabetes mellitus (hsa04930), respectively." (PMID 36499541, 2022).
colorectal cancer (21 papers, 2010 to 2026). A primary or metastatic malignant neoplasm that affects the colon or rectum. "TIMP1 and TNFRSF1B genes have been confirmed to take part in the pathogenesis of colorectal cancer and have prognostic value." (PMID 35480305, 2022). "Baseline plasma TNFRSF1B, a marker of inflammation and a soluble TNF antagonist, was significantly associated with an increased risk of human colorectal cancer." (PMID 30061500, 2018). "There is no report on the function of this polymorphism but it has been reported that higher expression levels of TNFRSF1B gene in colorectal cancer specimens from responding patients were observed compared with those from non-responding patients." (PMID 20646319, 2010). "Therefore, inhibition of Tnfrsf1b might be used as a strategy to prevent the progression of colorectal cancer to the liver, while IP6 might be used as a reliable way to inhibit the expression of Tnfrsf1b, thus achieving the effect of inhibiting tumor metastasis." (PMID 36118769, 2022).